RNU6-1028P (RNA, U6 small nuclear 1028, pseudogene)
Gene: Small nuclear RNA gene on chromosome 19 (19,232,855 to 19,232,947, forward strand). Ensembl gene ENSG00000252973.
Homologues: Orthologues: chimpanzee U6 (99% identical), macaque U6 (86% identical), mouse Gm55671 (65% identical). Paralogues in human: RNU6-1042P (85% identical), RNU6-116P (85% identical), RNU6-1230P (85% identical), RNU6-41P (85% identical), RNU6-71P (85% identical), RNU6-842P (85% identical), RNU6-891P (85% identical), RNU6-1011P (84% identical), RNU6-10P (84% identical), RNU6-12P (84% identical), RNU6-13P (84% identical), RNU6-187P (84% identical), and 1284 more.